CDKN2D (cyclin dependent kinase inhibitor 2D)
Description:
Interacts strongly with CDK4 and CDK6 and inhibits them.
Synonyms: INK4D; p19; p19-INK4D
Tractability: No criterion of Open Targets' tractability assessment is met for any kind of drug.
Gene: Protein-coding gene on chromosome 19 (10,566,460 to 10,569,059, reverse strand). Ensembl gene ENSG00000129355.
Subcellular location: Nucleus; Cytoplasm
Subcellular location (Human Protein Atlas): Nucleoplasm; Cytosol
Pathways (Reactome):
Cellular responses to stimuli: Oncogene Induced Senescence; Oxidative Stress Induced Senescence; Senescence-Associated Secretory Phenotype (SASP)
Cell Cycle: Cyclin D associated events in G1
Gene Ontology:
Molecular function: cyclin-dependent protein serine/threonine kinase inhibitor activity; protein binding; protein kinase binding
Biological process: autophagic cell death; DNA synthesis involved in DNA repair; negative regulation of cell growth; negative regulation of cell population proliferation; negative regulation of G1/S transition of mitotic cell cycle; negative regulation of intrinsic apoptotic signaling pathway in response to DNA damage; regulation of G1/S transition of mitotic cell cycle; response to retinoic acid; response to UV; response to vitamin D; negative regulation of cell cycle G1/S phase transition
Cellular component: cytoplasm; cytosol; nucleoplasm; nucleus; cyclin D2-CDK4 complex
Genetic constraint (gnomAD): Loss-of-function variants: 2 observed, 4.26 expected, observed/expected ratio (o/e) 0.47, 90% interval 0.19 to 1.43. That is too few expected variants to judge how well the gene tolerates losing a copy. Missense variants: 167 observed, 193.96 expected, observed/expected ratio (o/e) 0.86, 90% interval 0.76 to 0.98. Synonymous variants: 80 observed, 81.72 expected, observed/expected ratio (o/e) 0.98, 90% interval 0.82 to 1.18.
Homologues: Orthologues: chimpanzee CDKN2D (100% identical), macaque CDKN2D (99% identical), dog CDKN2D (90% identical), pig CDKN2D (90% identical), guinea pig CDKN2D (89% identical), mouse Cdkn2d (87% identical), rat Cdkn2d (86% identical), tropical clawed frog cdkn2d (61% identical), zebrafish cdkn2d (52% identical). Paralogues in human: CDKN2C (43% identical), ANKRD39 (27% identical).
Diseases named in the same sentence as CDKN2D in open-access papers:
CDKN2D is named in the same sentence as 36 diseases in open-access papers, as found by Europe PMC text mining. Sharing a sentence is not in itself a finding about the gene and the disease. The quoted sentences say what the papers report.
leukemia (3 papers, 2016 to 2024). A malignant (clonal) hematologic disorder, involving hematopoietic stem cells and characterized by the presence of primitive or atypical myeloid or lymphoid cells in the bone marrow and the blood. "In acute promyelocytic leukemia (APL), the fusion protein PML/RARα downregulates the expression of CDKN2D by suppressing its promoter activity, which in turn affects leukemia cell proliferation and differentiation." (PMID 39422621, 2024).
colorectal cancer (2 papers, 2018 to 2022). A primary or metastatic malignant neoplasm that affects the colon or rectum. "Specific methylation patterns of known transcriptionally silenced tumour suppressor genes in primary tumours have been shown previously; the CDKN2D promotor was differentially methylated in different types of colorectal cancer, but not specifically correlated with gene expression." (PMID 29748642, 2018).
esophageal carcinoma (2 papers, 2016 to 2021). A primary or metastatic malignant neoplasm involving the esophagus. "miR-451 inhibits esophageal carcinoma proliferation by targeting CDKN2D expression." (PMID 33718220, 2021). "In addition, overexpression of CDKN2D reverses the effect of miR-451, which contributes to esophageal carcinoma malignancy." (PMID 27183310, 2016).
liver cancer (2 papers, 2021 to 2023). An epithelial or non-epithelial malignant neoplasm that arises from the liver. "Then, we also explored the correlation between the expression of 11 ROS-related genes and TNM stages in liver cancer, and the findings showed that the expression of CDKN2D, G6PD, MSRA, OXSR1, PFKP, and STK25 was connected with TNM stages (P < 0.05)." (PMID 34795841, 2021).
melanoma (2 papers, 1999 to 2025). A malignant, usually aggressive tumor composed of atypical, neoplastic melanocytes. "For example, analyzing pathways linking disease CMM1 to known melanoma-associated genes CDKN2D and CDK4, with edge thickness representing attention weights, revealed a key pathway (CMM1 → MC1R → Mole → CDK4/CDKN2D) offering novel insights into melanoma pathogenesis." (PMID 40680165, 2025).
Alzheimer disease (1 paper, 2025). A progressive, neurodegenerative disease characterized by loss of function and death of nerve cells in several areas of the brain leading to loss of cognitive function such as memory and language. "Single-cell sequencing of the brains of Alzheimer’s disease patients shows that aging markers in excitatory neurons are consistent with Tau pathology, and CDKN2D has been identified as a prominent aging marker for Alzheimer’s disease." (PMID 39963130, 2025).
colon cancer (1 paper, 2022). "Additionally, this gene is a positive regulator of Wnt signaling, regulates the MYC oncogene, represses the cell cycle inhibitors CDKN2C/CDKN2D, and is a transcriptional driver of various oncogenes, contributing to the progression of colon cancer and other cancer types." (PMID 35992833, 2022).
female infertility (1 paper, 2023). Diminished or absent ability of a female to achieve conception. "CDKN2D (P19), a cyclin-dependent kinase inhibitor 2D, causes activation of the p19 signaling pathway, inhibits granulosa cell proliferation, and leads to female infertility." (PMID 38053145, 2023).
glioma (1 paper, 2014). A benign or malignant brain and spinal cord tumor that arises from glial cells (astrocytes, oligodendrocytes, ependymal cells). "Since the expression of CDKN2D is dependent on cell cycle phase, with expression lowest at mid-G1 and maximal during S-phase, the results implied that G1 arrest may be induced in glioma as a result of these four interventions." (PMID 25007077, 2014).
head and neck cancer (1 paper, 2019). A primary or metastatic malignant neoplasm affecting the head and neck.
hemangiosarcoma (1 paper, 2024). "In vivo mouse experiments established p19INK4d as a canonical tumor suppressor as mice having a complete deletion of CDKN2D gene showed increased frequency of development of wide range of tumors such as pituitary and lung adenomas, lymphomas, hemangiosarcoma, thyroid cancer, and insulinoma." (PMID 38561743, 2024).
Hyperinsulinemia (1 paper, 2024). An increased concentration of insulin in the blood. "In contrast, we observed the additive effect of hyperinsulinemia and JAKi on the cell cycle-controlling genes CDKN2D/p19, EIF2S3B, GREM2, and YBX3." (PMID 39768214, 2024).
cancer (23 papers, 2007 to 2025). A tumor composed of atypical neoplastic, often pleomorphic cells that invade other tissues. "Loss of CDKN2D in cancer cells is one event which is generally associated to a more malignant phenotype." (PMID 20805891, 2010). "Cyclin-dependent kinase inhibitors: The family of cyclin-dependent kinase inhibitor genes, CDKN2A (p16-INK4), CDKN2B (p15-INK4b), CDKN2C (p18-INK4c), and CDKN2D (p19-INK4d), are tumor suppressor genes generally inactivated in human cancers." (PMID 35056738, 2022). "In the future, it will be necessary to use drugs and combinations of these in cancers marked by Cdk8 and Cdkn2d expression." (PMID 36292630, 2022). "While Cdkn3 is expressed mostly in cancer, other CDKIs are categorized into the Cip/Kip family (p21 encoded by cdkn1a, p27/cdkn1b, and p57/cdkn1c) and INK4 family (p16/cdkn2a, p15/cdkn2b, p18/cdkn2c, and p19/cdkn2d)." (PMID 39668249, 2025). "However, CDKN2D alterations are very rare in human cancers, and according to the TCGA database, the rate is below 1%." (PMID 38561743, 2024). "The expression of CDKN2A, CDKN2B, CDKN2C, and CDKN2D was analyzed in 20 types of cancers." (PMID 35771229, 2022). "After OTX015 SCLC resistant and sensitive cells differed presenting an up-regulation of CDKN2D (P19) in resistant cells, and of CDKN1C (P57) in the sensitive cells, changes that could be linked with the different sensitivity to anti-cancer drugs." (PMID 27835869, 2016). "In many cancer cell types, 1,25-(OH)2D3 directly arrests the cell cycle in the G0/G1 phase by downregulating cyclin-dependent kinases (CDKs: CDK4, CDK6) and repressing the genes that encode cyclins D1 and C (CCND1, CCNC) and CDK inhibitors p21CIP1/WAF1 (CDKN1A), p27KIP1 (CDKN1B) and p19 (CDKN2D)." (PMID 35406059, 2022). "Moreover, ChIP-chip assays yielded a total of 48 genes enriched in at least three of the seven primary samples including genes associated with cell cycle such as ARGHEF2, CCNA2, CDKN2D, GAK2, ORCL6, PCPNP, and TACC1 and genes associated with cancer such as AR, AXIN2, IKBKG, ETS1, PTPN11, and WNT2B." (PMID 23300998, 2013). "In our results, calycosin affected two check points gene transcription; for example TFDP-1 and SKP2 were markedly downregulated and CDC2 and CCNB1 were upregulated expression and downregulated expression of CDKN2D which may block the G1/S and G2/M transition in cancer cells." (PMID 24455688, 2013). "The CDKN2D/p19INK4d gene is repressed by ΔNp73α, and E2F4-5 in both 38HK and CAL51 cancer cell lines." (PMID 36883841, 2023). "The expression of CDKN2A, CDKN2B, CDKN2C, and CDKN2D was positively correlated with the T stage, and the expression of CDKN2A, CDKN2B, and CDKN2C was positively correlated with the pathological stage, indicating that patients with more advanced cancer tended to express higher mRNA levels of INK4." (PMID 35771229, 2022).
tumor (22 papers, 2012 to 2025). "We found that low expression of CDKN2D correlated with poor patient survival and known NB risk factors such as MNA, suggesting a tumor suppressor role." (PMID 32337068, 2020). "CDKN2D has been demonstrated to induce tumor cell apoptosis through the cyclin D-CDK4/6-INK4-Rb pathway." (PMID 24137329, 2013). "Gene cluster ‘4’ (significant for sample-cluster ‘7’): This gene-cluster is slightly down-regulated for sample-cluster ‘7’, and GO analysis extracts two genes, CDKN1B/p27 and CDKN2D/p19, which are key tumor suppressor genes for aggresive neoplasms." (PMID 22427814, 2012). "Mice lacking two Ink4 genes, such as Cdkn2a/Cdkn2b or Cdkn2a/Cdkn2d, display increased tumor susceptibility compared to p16INK4a-null mice." (PMID 38561743, 2024). "Along with CDKN2A, other INK4 family members, CDKN2B, CDKN2C, and CDKN2D, also showed a good ability to distinguish tumor from normal tissue, particularly CDKN2C, suggesting that they can be used as biomarkers for the screening, diagnosis, and prognosis prediction of HCC." (PMID 35771229, 2022). "Taken together, upregulation of miR-451a inhibited cell proliferation and induced apoptosis in NOZ and TGBC2TKB cells, partly through regulation of MIF, PSMB8 and CDKN2D, suggesting that miR-451a has a tumor-suppressing role and could be a novel therapeutic target in GBC cells." (PMID 34112884, 2021). "Researchers found that in tumor biopsies resistant to palbociclib, CCND3, CCNE1, and CDKN2D are persistently elevated before palbociclib used, all three genes are known E2F1 transcription targets, suggesting persistent E2F activity in resistant tumors." (PMID 34123801, 2021). "Conversely, loss of the endogenous CDK4/6 inhibitors (CDKN2A, CDKN2B, CDKN2C, and CDKN2D) or RB-family (RB1, RBL2, and RBL1) are also observed in specific tumor settings, in total the RB-pathway is subject to genetic perturbation in greater than 30% of tumors." (PMID 32242058, 2020). "As expected, SETD7, H3K4me2, CDKN2D, and ZBTB20 are significantly higher in HCC tumor tissues than in ANLTs." (PMID 27183310, 2016). "The genomic breakpoint was identified in intron 1 of CDKN2D and intron 2 of WDFY2 in patient tumor, providing direct evidence that this is a fusion gene." (PMID 24675677, 2014). "The present study identified that LSCC had increased CDKN2D expression compared with RSCC, suggesting an additional mechanism for the differences in tumor size and survival outcome between LSCC and RSCC." (PMID 24137329, 2013). "Downregulated TFDP-1, CDKN2D, and SPK2 and upregulated CDC2 and CCNB1 might affect cell cycle of tumor cells." (PMID 24455688, 2013). "Additionally, the first one is implicated in the apoptosis pathway and GC suppression of proliferation via suppression of cyclin-dependent kinase inhibitor 2D (CDKN2D), MIF, and PSMB8, having a prognostic value, whereas the second is in tumor progression, proliferation, as well as invasion." (PMID 40650114, 2025).
infection (2 papers, 2010 to 2026). The state of being infected such as from the introduction of a foreign agent such as serum, vaccine, antigenic substance or organism. "Genes involved in cell cycle CDK4, CDK5, Cyclin E1, CKN2B, CDKN2D were down-regulated at all time-points post infection." (PMID 20828378, 2010). "Additionally, as the duration of infection increases, aging-related genes Plk1, Cenpa, Bub1b, H2afx, and Cdkn2d were activated, suggesting that infection may initiate cellular senescence." (PMID 41827050, 2026).
CDKN2D also shares sentences with these, for which no sentence is quoted: hepatocellular carcinoma (4 papers); breast carcinoma (2); prostate tumor (2); renal fibrosis (2); acute monocyte leukemia (1); acute promyelocytic leukemia (1); allergic asthma (1); breast tumors (1); endometriosis (1); gastric cancer (1); insulinoma (1); invasive breast carcinoma (1); lung adenoma (1); lymphoma (1); male infertility (1); malignant glioma (1); medulloblastoma (1); osteosarcoma (1); pancreatic cancer (1); testicular germ cell tumor (1); thyroid cancer (1).